INS (insulin)
Diseases named in the same sentence as INS in open-access papers (continued):
Sharing a sentence is not in itself a finding about the gene and the disease.
Hypoglycemia (continued). "However, its use has been linked to an increased risk of neonatal hypoglycemia due to its ability to inhibit insulin secretion from pancreatic beta cells, which may result in decreased glucose uptake by tissues." (PMID 37529595, 2023). "Thus, in the setting of impaired insulin and glucagon responses to hypoglycemia, recurrent hypoglycemia induces a syndrome of Hypoglycemia Associated Autonomic Failure (HAAF) that is composed of an impaired awareness of hypoglycemia (IAH) and a blunted counterregulatory response." (PMID 37942482, 2023). "The increased risk of hypoglycemia may be related to improved insulin sensitivity." (PMID 36593495, 2023). "Moreover, a ketogenic diet and SGLT-2 inhibitors may rarely raise the risk of hypoglycemia, particularly in diabetics who are taking insulin or other glucose-lowering drugs." (PMID 37998523, 2023). "CH could be classified into focal or diffuse forms and is characterized by increased insulin secretion by pancreatic beta-cells, causing hypoglycemia associated with low/normal levels of ketones and fatty acids, absence of metabolic acidosis, and positive glycemic response to glucagon." (PMID 37630734, 2023). "However, a few studies demonstrated that insulin use increased the risk of dementia, which might be related to an increased risk of hypoglycemia." (PMID 36804018, 2023). "In conclusion, the results of this meta-analysis add to the evidence that metformin may be particularly useful in women with GDM at high risk for neonatal hypoglycemia, women who want to limit maternal and fetal weight gain, or women with an inability to afford or use insulin safely." (PMID 36593391, 2023). "However, an important issue that must be analyzed is effectiveness whether the new weekly applied insulin increases or diminishes the risk of hypoglycemia." (PMID 37249450, 2023). "Therefore, it is possible that the reduced risk of hypoglycemia in patients treated with insulin degludec could be responsible for the observed reduction in the risk of CVD." (PMID 36830610, 2023). "Although this is not sufficient for people using first-generation long-acting insulins, reducing the meal-related dose of short-acting insulin after evening exercise may reduce the risk of nocturnal hypoglycaemia in people with type 1 diabetes on insulin degludec." (PMID 36879098, 2023). "However, But the risk of hypoglycemia with insulin still worsens glucose fluctuations." (PMID 37255975, 2023). "The relative insulin overdose may have caused hypoglycemia during the operation." (PMID 38134112, 2023). "However, there is a risk of hypoglycaemia in premature babies when combined with insulin treatment." (PMID 38004396, 2023). "For example, neonatal hypoglycaemia was associated with marked increases in lipid abundance in maternal blood in the first trimester, suggesting maternal lipolysis (e.g. due to insufficient insulin dosing or energy restriction due to nausea and vomiting in pregnancy)." (PMID 37442824, 2023). "The high rates of DM remission, in conjunction with the risk of post-operative hypoglycemia principally due to excessive rebound hyperinsulinemia require vigorous glucose monitoring post-operatively and appropriate down-titration of anti-diabetic regimens, especially in insulin-treated patients." (PMID 37731140, 2023). "We find that novel technologies, ranging from continuous glucose monitoring systems, insulin pumps and decision support tools to the most advanced hybrid closed loop systems, improve important measures like HbA1c, time in range, and glycemic variability, while reducing hypoglycemia risk." (PMID 37794113, 2023). "Finally, we investigated the pattern of beta cell deactivation after removal of stimulus, to assess the possibility of prolonged deactivation delays that could correlate with continued insulin secretion and risk for hypoglycemia in type 2 diabetics." (PMID 38292770, 2023).
Hypoglycemia (continued). "Furthermore, multivariate logistic regression analysis revealed that the course of disease, BMI, fasting C-peptide and creatinine were independent risk factors for hypoglycemia after intensive insulin therapy, while blood glucose monitoring means during treatment were protective factors." (PMID 38223574, 2023). "However, the combination of oral antidiabetics with a risk of hypoglycemia (sulphonylureas) or insulin with beta-blockers might result in masking the first symptoms of hypoglycemia (tachycardia, tremor)." (PMID 36817138, 2023). "The NICE guidelines recommend initiation with human neutral protamine Hagedorn (NPH) insulin, whereas long-acting basal insulin has been suggested for patients with a higher risk of developing hypoglycemia, and in circumstances where twice-daily injection may be burdensome." (PMID 36650625, 2023). "Consequently, health care providers should attach great importance to patients who receive insulin or insulin secretagogues, improve health education, conduct patient-centered treatment, and regularly assess the psychological status to decrease the risk of hypoglycemia and improve FoH in patients." (PMID 36434039, 2022). "Therapies that carry a risk of developing hypoglycemia (a drop in blood sugar below normal values) such as insulin analogs and sulfonylurea (which increase insulin secretion), may be associated with increased risk of falling which in turn may increase the risk of fractures." (PMID 35388291, 2022). "However, appliance of the IER diet among patients on hypoglycemic drugs, such as insulin or sulfonylurea, may contribute to the increased risk of hypoglycemia." (PMID 35406122, 2022). "Importantly, Smad3-deficient mice show a slightly higher level of blood insulin, pancreatic insulin content, and moderate hypoglycemia with augmented glucose tolerance, although these mice have similar islet morphology and β cell mass compared with the wild-type mice." (PMID 35327565, 2022). "Therefore, the degeneration of peripheral nerves might be caused by transient hypoglycemia and subsequent impairment of insulin secretion." (PMID 35005553, 2022). "Of patients taking insulin, 7%–15% experience at least one episode of hypoglycemia per year, and 1%–2% found to have severe hypoglycemia (i.e., requiring assistance from others for treatment), and hypoglycemia has been associated with poor outcomes and higher rates of death." (PMID 36149907, 2022). "However, patients receiving insulin or insulin secretagogues have a high risk of hypoglycemia and may be more susceptible to FoH4,23." (PMID 36434039, 2022). "Moreover, the risk of hypoglycemia associated with insulin treatment might lead to defensive snacking and less physical exercise." (PMID 36397092, 2022). "With this method, insulin is infused intravenously at a constant rate sufficient to cause plasma glucose levels to fall, alongside a variable intravenous glucose infusion titrated against frequent glucose measurements to achieve hypoglycaemia at predefined glucose plateaus." (PMID 35867127, 2022). "The most recently published RCT evaluated the effectiveness of technosphere insulin with insulin lispro, and found that HbA1c was unchanged in both groups, however, the technosphere insulin was associated with improved post-meal glucose and a lower risk of hypoglycemia in a 16-week period." (PMID 35509734, 2022). "In terms of prevention strategies for PA-associated hypoglycemia, carbohydrate feeding often requires less pre-planning compared to basal and bolus adjustments and therefore, may be more common than strategies based on insulin reduction." (PMID 36237197, 2022). "Notably, the most immediate risk of IF is hypoglycemia in patients taking hypoglycemic medications, particularly insulin (both postprandial and basal) and sulfonylureas (including short-acting metronidazole), and caution should be exercised when administering IF to this group of patients." (PMID 35685418, 2022).
Hypoglycemia (continued). "In Group-17/18, insulin therapy was significantly less often initiated (33%), which may have indicated higher glycemic levels in the third trimester of pregnancy and an increased risk of neonatal hypoglycemia." (PMID 35334574, 2022). "However, this could result in an increased risk of hypoglycaemia in some dogs with a duration of insulin action > 12 h." (PMID 35152907, 2022). "In those treated with SU and insulin, time spent in hypoglycemia and hypoglycemic event rate was strongly associated with glycemic control, with differences in HbA1c explaining 33.1% (p=<0.001) and 20.7% (p=0.005) of variation in time below 3 mmol/L for SU and insulin, respectively." (PMID 35450869, 2022). "Therefore, it is considered that an MPC-based artificial pancreas system could improve glucose control while reducing the risk of hypoglycemia, compared to conventional insulin therapy in long-term (> 1 month) use." (PMID 36494830, 2022). "The reduction/omission of insulin therapy is likely to be linked to psychological processes other than emotional eating, such as denial of the disease, self-destructive and suicidal ideation, and fear of severe hypoglycemia as observed in the study of Schober44." (PMID 36528643, 2022). "However, less frequent inclusion of insulin may result in higher postprandial glycemia in the third trimester of pregnancy in mothers, thus increasing the risk of neonatal hypoglycemia immediately after delivery." (PMID 35334574, 2022). "The question arises whether the low fasting plasma glucose target achievement is rather causally related to the significant risk for any symptomatic or even severe hypoglycemia associated with basal insulin treatment in the studies analyzed in the present study." (PMID 35942330, 2022). "In brief, insulin may be useful in patients with compensated and decompensated liver cirrhosis, but close titration of insulin doses and frequent monitoring of glucose levels are needed to avoid the risk of hypoglycemia." (PMID 35252271, 2022). "However, improper administration of insulin injections may increase the risk of hypoglycemia in pregnant women." (PMID 36530712, 2022). "However, using empagliflozin along with insulin and/or insulin secretagogues may raise the risk of hypoglycemia." (PMID 36147179, 2022). "Medications other than insulin may also increase the risk of exercise-induced hypoglycemia." (PMID 36231598, 2022). "The insulin concentrations needed to shift potassium into cells remain above the threshold concentration only transiently; however, it remains high enough to lower blood glucose (glycaemic concentrations) for a longer period, increasing the risk of hypoglycaemia." (PMID 35552566, 2022). "However, T2D patients who use other types of anti-diabetic medication, especially insulin, might be at risk of developing hypoglycemia while using this medication in combination with the prolonged forms of fasting." (PMID 34067055, 2021). "In addition, we investigated the modulatory effects of exogenous (CDCA) and endogenous bile acids (by COL administration) on meal-induced plasma concentrations of glucose, including the risk of hypoglycemia, and other glucoregulatory hormones including insulin, glucagon, CCK, neurotensin and FGF-19." (PMID 34084153, 2021). "When initiating a GLP‐1RA, a lower dose of insulin may be needed to reduce hypoglycaemia risk." (PMID 33098260, 2021). "Such factors contribute to wide fluctuations in blood glucose levels and exogenous insulin requirements, which become even more impaired by the alteration of the pharmacokinetics of exogenous insulin and hypoglycemic agents and predisposition to asymptomatic hypoglycemia." (PMID 34625090, 2021). "Moreover, an Indian study of patients with T2D revealed that the COVID-19 lockdown has been shown to increase the risk of hypoglycemia in patients with T2D, especially those receiving sulfonylureas (SU), insulin and HCQ, and especially in patients with associated co-morbidities." (PMID 34248841, 2021).
Hypoglycemia (continued). "The experience we report here suggests that, in well-instructed and strongly motivated patients observing Ramadan fasting, technology may greatly limit the risk of hypoglycaemia, while helping to achieve fair glucose control, reduce insulin doses and provide empowerment and satisfaction." (PMID 33683423, 2021). "Therefore, linagliptin may help to decrease glucose variation as a risk factor for hypoglycemia in hospitalized KT patients treated with basal bolus insulin regimen." (PMID 33808901, 2021). "However, as insulin increases the potential risk of hypoglycaemia, setting up less stringent targets for patients at risk of hypoglycaemia or who are otherwise vulnerable may be considered." (PMID 33098260, 2021). "However, a concomitant use of insulin or insulin secretagogues (glinides, sulfonylureas) may increase the risk of hypoglycemia." (PMID 34068655, 2021). "With a 90-minute onset of action and 24-hour duration of action, patients with type 1 DM (T1DM) or type 2 DM (T2DM) receiving insulin glargine may have lower risk of hypoglycemia, particularly nocturnal hypoglycemia, compared with intermediate-acting human insulin such as neutral protamine Hagedorn." (PMID 34133466, 2021). "Finally, while these experiments are challenging to implement, it is not possible to reduce the time and the complexity of these studies because of the large variation in insulin sensitivity seen among different people and the risks associated with hypoglycemia." (PMID 34484102, 2021). "Greater weight loss in hypoglycemia patients has been reported in previous studies and might overstrain metabolic adaptations after bariatric surgery, especially when occurring over a short period, leading to postprandial overexcretion of insulin." (PMID 33624213, 2021). "Notably, diabetic kidney disease (DKD), a co-morbidity already associated with increased risk of hypoglycaemia in non-COVID-19 infected patients due to factors such as reduced insulin clearance and degradation, was the co-morbidity most frequently associated with hypoglycaemia during lockdown." (PMID 34248841, 2021). "Insulin infusion is therefore modified every few minutes based on new glucose values received by CGM: CLC increases insulin infusion when glucose values are increasing and decreases or suspends insulin infusion in case of significant reduction of glucose levels to minimize the risk of hypoglycemia." (PMID 33755854, 2021). "Exogenous insulin therapy may cause hypoglycemia and in turn increased risk of MACE and death." (PMID 34158057, 2021). "Moreover, long-term insulin treatment lowers glucose and results in increased risk of hypoglycemia." (PMID 33708999, 2021). "However, the slightly increased insulin levels make the infant more susceptible to hypoglycemia." (PMID 33633228, 2021). "Hypersecretion of insulin from the tumour may cause hypoglycaemia." (PMID 34170845, 2021). "Thus, the risk of nocturnal confirmed hypoglycemia was significantly lower in the twice-daily IDegAsp group (OR 0.52, 95% CI 0.42 to 0.65, I2 = 23.9%) than that in the twice-daily conventional premixed insulin group." (PMID 34564455, 2021). "This was already underlined in 1985, when Schiffrin and Parikh examined the effects of modifying premeal insulin doses before a 45-min exercise session in 13 adolescents with T1D and found that a reduction of 50% of the premeal dose proved an effective method to reduce the risk of hypoglycemia." (PMID 34512541, 2021). "However, they also highlight that insulin glargine U300 and insulin degludec may be associated with less hypoglycemia compared with insulin glargine U100 or insulin detemir." (PMID 34636912, 2021). "Notably, to reduce the risk of hypoglycemia caused by insulin administration and realize self-regulation, the microneedles are made glucose-responsive, relying on chemical-reaction-induced disassembly of insulin complex." (PMID 33623910, 2020).
Hypoglycemia (continued). "However, the risk of hypoglycemia may be increased when SGLT2 inhibitors are used in combination with insulin and/or insulin secretagogues." (PMID 32403420, 2020). "Pharmacodynamic variability is particularly challenging for insulin, due to the large absorption variability associated with oral dosing in combination with a narrow therapeutic window with an overdose being associated with potentially life-threatening hypoglycaemia." (PMID 32719315, 2020). "The use of ACE inhibitors has been associated with increased insulin sensitivity in diabetic patients, and their concomitant use with antidiabetic therapies may facilitate their blood glucose-lowering effect with a concomitant risk of hypoglycemia." (PMID 32151247, 2020). "Therefore, assessing the risk of hypoglycemia is an important aspect of intensive insulin therapy." (PMID 33015194, 2020). "In addition to insulin use, what was associated with hypoglycemia was worth discussing." (PMID 32149152, 2020). "In addition to fetal growth, the fluctuations of insulin and glucose lead to hypoxia-ischemia, hypoglycemia, and iron deficiency, which may adversely affect the developing brain, specifically the hippocampus." (PMID 32751314, 2020). "However, the administration of insulin requires close monitoring, and it might be associated with an increased risk of hypoglycemia, especially with the depleted glycogen status." (PMID 32560535, 2020). "Compared with human soluble insulin, the rapid-acting analogs were developed to accelerate insulin absorption, and simultaneously minimize postprandial glucose rise more effectively and lower the risk of hypoglycemia due to the high exogenous insulin concentrations for longer needed." (PMID 32850735, 2020). "Intensive insulin therapy may be the major cause of hypoglycemia." (PMID 33224911, 2020). "As inadequate insulin titration and fear of hypoglycaemia were stated as the most common causes negatively impacting glycemic control, principles of insulin self-titration, and prevention and management of hypoglycaemia, could be areas of focus for patient education programs." (PMID 32569176, 2020). "Importantly, the release rate of insulin was also reduced when the glucose levels reached the normoglycemic level, which could avoid the risk of hypoglycemia." (PMID 32629825, 2020). "Furthermore, low-dose-treated diabetic NOD mice, which failed to return to normoglycaemia, continue to gain weight and appear well, suggesting that even low doses of insulin gene therapy vector can have beneficial effects while avoiding the risk of causing hypoglycaemia." (PMID 30514969, 2019). "Here we discuss the pathophysiological foundation of hypoglycemia - situations caused by increased insulin production or sensitivity - but we also focus on different cytokines which could cause hypoglycemia, especially IGF-II production in what are called nonislet cell tumors." (PMID 31777577, 2019). "However, when levels are further increased with exogenous insulin, these pathways are further stimulated, which may readily cause hypoglycemia." (PMID 30357355, 2019). "Similarly, a prior study found that, in the 20-item ITAS, which was designed to be applicable to both insulin-naive and insulin-treated patients, items pertaining to weight gain and increased risk of hypoglycemia had relatively lower factor loadings than other items." (PMID 30807441, 2019). "Thus, the possible mechanism that explains the causal association of ciprofloxacin and hypoglycemia could be increased insulin release via blockade of ATP-sensitive potassium channels in the beta-cells of the pancreas." (PMID 31078137, 2019). "Furthermore, insulin therapy was associated with hypoglycemia." (PMID 30700277, 2019). "However, intensification of insulin therapy increases the risk of weight gain and hypoglycemia." (PMID 30871141, 2019).